ISLR2 (immunoglobulin superfamily containing leucine rich repeat 2)
Description:
Required for axon extension during neural development.
Synonyms: KIAA1465; LINX
Tractability: Small molecule: it belongs to a druggable protein family. Antibody: UniProt places it where antibodies can reach, with medium confidence; UniProt predicts a signal peptide or a membrane-spanning region; its Gene Ontology location is reachable by antibodies, with medium confidence. PROTAC: its protein half-life has been measured.
Gene: Protein-coding gene on chromosome 15 (74,100,311 to 74,138,540, forward strand). Ensembl gene ENSG00000167178.
Subcellular location: Cell membrane
Gene Ontology:
Molecular function: protein binding
Biological process: positive regulation of axon extension
Cellular component: cell surface; plasma membrane
Genetic constraint (gnomAD): Loss-of-function variants: 17 observed, 29.14 expected, observed/expected ratio (o/e) 0.58, 90% interval 0.4 to 0.88. The upper end of that interval is the gene's LOEUF score, 0.88, which puts it in group 3 of 6, group 1 being the genes least tolerant of losing a copy. Missense variants: 883 observed, 1,060.2 expected, observed/expected ratio (o/e) 0.83, 90% interval 0.79 to 0.88. Synonymous variants: 508 observed, 501.92 expected, observed/expected ratio (o/e) 1.01, 90% interval 0.94 to 1.09.
Homologues: Orthologues: macaque ISLR2 (97% identical), pig ISLR2 (91% identical), dog ISLR2 (90% identical), mouse Islr2 (89% identical), rat Islr2 (89% identical), guinea pig ISLR2 (84% identical). Paralogues in human: ISLR (28% identical), LRRN4 (12% identical), LRRN4CL (5% identical).
Diseases named in the same sentence as ISLR2 in open-access papers:
ISLR2 is named in the same sentence as 15 diseases in open-access papers, as found by Europe PMC text mining. Sharing a sentence is not in itself a finding about the gene and the disease. The quoted sentences say what the papers report.
breast carcinoma (4 papers, 2023 to 2024). "We identified KDEL motif-containing protein 2 (KDELC2) and RCC, as well as Copine-1 (CPNE1) and Immunoglobulin superfamily containing leucine-rich repeat protein 2 (ISLR2) and breast cancer as having a high posterior probability of a shared variant (i.e. PPH4 > 0.8)." (PMID 38527997, 2024). "Similarly, GDI2 (OR: 0.85, 95% CI 0.80–0.91), ISLR2 (OR: 0.87, 95% CI 0.82–0.93), and CTSF (OR: 1.14, 95% CI 1.08–1.21) could potentially be targets for breast cancer." (PMID 37735436, 2023).
congenital hydrocephalus (2 papers, 2024). Hydrocephalus that is present at birth. "ISLR2, expressed in the brain and testis, is linked to congenital hydrocephalus, and predicted to be involved in the positive regulation of axon extension during neural development." (PMID 39408633, 2024). "Moreover, our study identifies the downregulation of specific genes, such as L1CAM, PCDH9, ISLR2, ADAMTSL2, and B4GAT1, which have been previously well characterized as playing an important role in congenital hydrocephalus and aqueductal stenosis." (PMID 39118132, 2024). "Moreover, downregulation of multiple proteins associated with congenital hydrocephalus (e.g., L1CAM, PCDH9, ISLR2, ADAMTSL2, and B4GAT1) points to a possible shared molecular foundation between congenital hydrocephalus and iNPH." (PMID 39118132, 2024).
Hydrocephalus (2 papers, 2018 to 2022). Hydrocephalus is an active distension of the ventricular system of the brain resulting from inadequate passage of CSF from its point of production within the cerebral ventricles to its point of absorption into the systemic circulation. "ISLR2 is involved in axon guidance in brain development, and ISLR2 deficiency leads to severe hydrocephalus in mice." (PMID 35668171, 2022).
meningioma (2 papers, 2023 to 2025). A generally slow growing tumor attached to the dura mater. "Interestingly, ISLR2, AMH, and lncRNA-GOLGA6A-1 transcription is controlled by several transcription factors including KLF4, which is linked to activating mutations of meningiomas." (PMID 38001599, 2023).
autism (1 paper, 2019). Persistent deficits in social interaction and communication and interaction as well as a markedly restricted repertoire of activity and interest as well as repetitive patterns of behavior. "It is worth noting that ISLR2 and SOCS2 are critically involved in regulating typical axon guidance and neuronal differentiation during neural development, processes recently shown to be disturbed in the neocortex of children with autism." (PMID 31681403, 2019).
COVID-19 (1 paper, 2023). A disease caused by infection with severe acute respiratory syndrome coronavirus 2. "Sets of co-expressed genes involved in COVID-19 susceptibility (ISLR2 and ACE2) were found to be significantly enriched in LAA GWAS." (PMID 37686257, 2023).
Hypertension (1 paper, 2023). The presence of chronic increased pressure in the systemic arterial system. "ISLR2 was found to be associated with hypertension, and SFTPB displayed an association with Granulysin." (PMID 37735436, 2023).
pseudoexfoliation syndrome (1 paper, 2022). "Interactions of ISLR2 with ret proto-oncogene was involved in regulating the development of the gastrointestinal tract, and alterations of ISLR2 expression levels were found to be associated with pseudoexfoliation syndrome." (PMID 36136577, 2022).
cancer (2 papers, 2016 to 2023). A tumor composed of atypical neoplastic, often pleomorphic cells that invade other tissues. "Phenotype scanning revealed that seven out of the thirteen identified proteins (KDELC2, GSTP1, CTSS, CPNE1, ISLR2, SFTPB, and ICAM5) were associated with other traits, but none of these traits were likely to bias the associations between identified proteins and cancers." (PMID 37735436, 2023).
ISLR2 also shares sentences with these, for which no sentence is quoted: Aqueductal stenosis (1 paper); brain tumors (1); gout (1); meningitis (1); prostate carcinoma (1); sarcopenia (1).